HOXC10 (homeobox C10)
Diseases named in the same sentence as HOXC10 in open-access papers (continued):
Sharing a sentence is not in itself a finding about the gene and the disease.
cancer (continued). "HOXC10 is overexpressed in many human cancers, and our discovery highlights that lncRNA HMS sustains the HOXC10 mRNA levels to maintain the invasive phenotypes of cancer cells." (PMID 34302808, 2021). "Homeobox C10 (HOXC10), as a member of the homeobox gene family, can significantly enhance cell proliferation in cancer, and can be used as a marker for cancer diagnosis or progression evaluation." (PMID 35201457, 2021). "Our review has described the roles and mechanisms of HOXC10 in the different processes of human cancers." (PMID 34113572, 2021). "Aberrant overexpression of HOXC10 and its role in cancer progression has been reported in several types of cancers." (PMID 32687064, 2020). "In this case, hypomethylation leads to HOXC10 overexpression, the downstream effects of which include increased of proliferation and the migration of cancer cells." (PMID 32635388, 2020). "As a master regulator of embryonic morphogenesis, homeodomain-containing gene 10 (HOXC10) has been found to promote progression of human cancers and indicate poor survival outcome." (PMID 31528218, 2019). "Overexpression of HOXC10 frequently detected in various cancers 12,18,22, promotes the growth and metastasis of malignant cells, and has a negative impact on the clinical outcome." (PMID 31528218, 2019). "Recent studies showed that abnormal HOXC10 expression contributed to the survival of cancer cells 11,23." (PMID 31528218, 2019). "Of these, key cancer-associated genes shown to be upregulated by the SySa fusion were downregulated by TAK-981 treatment, including CDX2, HOXA10, SUZ12, TYMS, AURKB, and HOXC10 and SMC2." (PMID 40804185, 2025). "Our HOXC10 /NOD1/ERK axis pathway fits with NOD1 regulating of cancer metastasis." (PMID 39191757, 2024). "Tartrate-resistant acid phosphatase (TRAP) staining revealed that the inhibition rates TRAP+ osteoclasts induced by the conditioned medium from HOXC10-inhibited cancer cells reached 55.2%–65.2% compared to those of the TRAP+ osteoclasts induced by control cell conditioned medium." (PMID 39191757, 2024). "Furthermore, qPCR results showed a marked increase in MMP9 transcription was observed from HOXC10 overexpression cancer cells conditioned medium induced osteoclasts, which were partially abrogated by ERK1/2 inhibition." (PMID 39191757, 2024). "We found elevated homeodomain-containing gene C10 (HOXC10) showed dual roles in cancers’ prognosis." (PMID 38154103, 2023). "The correlations of HOXC10 with immune-related genes presented dual roles in different cancers." (PMID 38154103, 2023). "In addition, it has been recently reported that HOXC10 plays an important role in the development of multiple cancers, including breast cancer, osteosarcoma, glioma and thyroid cancer." (PMID 37733108, 2023). "We next evaluated the correlations of HOXC10 with immune infiltration in cancers." (PMID 38154103, 2023). "HOXC10 also induces drug resistance in cancers by promoting the DNA repair pathway." (PMID 34113572, 2021). "HOXC10 was found to contribute to drug resistance in cancers by fine-tuning DNA repair." (PMID 34113572, 2021). "Homeobox C10 (HOXC10) has been reported to participate in various cancers." (PMID 35201457, 2021). "Elevated HOXC10 also accelerates cancer progression via the PI3K/AKT signaling pathway." (PMID 34113572, 2021). "Thus, we conclude that in the absence of HMS, HOXC10 3′UTR is destabilized leading to decreased levels of HOXC10 protein, which leads to a decrease in the cancer-related phenotypes of U2OS cells." (PMID 34302808, 2021). "Importantly, this study is the first to find that the HOXC10 gene can positively regulate the Slug gene by regulating cancer metastasis." (PMID 32897245, 2020).
cancer (continued). "Moreover, HOXC10 positively regulated Slug expression, altering the migration ability of cancer cells." (PMID 32897245, 2020). "Given the data above in bone and cancer, HOXC-AS3 upregulation appears to be pro-growth and linked with expression of HOXC10, therefore their increase in the current study maybe hypothesised to be a co-operative and compensatory drive to maintain aged muscle." (PMID 32958812, 2020). "Next, we investigated whether STAT3i could sensitize cancer cells to HOXC10 inhibition in vivo." (PMID 39191757, 2024). "However, the biological function and clinical role of HOXC10 in pan-cancer remains vague." (PMID 38154103, 2023). "Thus, we have conducted a systematic review of the HOXC10 gene and its role in cancer." (PMID 34113572, 2021). "Nonetheless, other HOX family members, such as HOXC10, have been reported as hypermethylated in ESCC, supporting the broader relevance of HOX genes in cancer epigenetics." (PMID 40699796, 2025). "Next, we analyzed the expression of HOXC10 in the primary and metastasis subgroups of pan-KRAS-mutant cancer using The Cancer Genome Atlas (TCGA) datasets." (PMID 39191757, 2024). "The HOXC10 gene, a member of the HOX family, has been reported abnormally expressed in several cancers." (PMID 37733108, 2023). "Some pathways showed dual roles such as Kras signaling, interferon gram and alpha response, IL6/JAK/STAT3, IL2/STAT5 signaling were negatively enriched in HOXC10 for CESC, COAD, ESCA, HNSC but were positively enriched in HOXC10 for other cancers." (PMID 38154103, 2023). "The involvement of HOXD10, HOXD11, HOXD1, HOXC4, HOXC10, and HOXA11, in the cell cycle and the EMT, confirm their role in the cancer-related signaling pathways." (PMID 35562533, 2022). "Through VENN analysis, we detected 603 upregulated and 1043 downregulated DEGs overlapping in the three cancer cell lines, including 16 upregulated TFs (e.g., HOXA2, HOXB2, HOXC10, and NKX2-1) and 36 downregulated TFs (e.g., BACH1 and CDX1), respectively." (PMID 32156290, 2020). "Likewise, the buccal mucosa-derived H157 (RRID: CVCL_2468) cancer cell lines showed overexpression of HOXA10, HOXC6, HOXC9, HOXC10 and HOXD11 which was consistent with the cancer of the buccal mucosa." (PMID 35710803, 2022). "HOXC10, as a member of the HOX family of genes, significantly enhances the proliferation, invasion and metastasis of cancer cells, and may be useful as a marker for cancer diagnosis or progression evaluation 11,12." (PMID 31528218, 2019). "The results showed that some HOX genes in pan-cancer had significant strong correlation (R≥0.8): HOXA9 with HOXA10, HOXB5 with HOXB6 and HOXB8, HOXB8 with HOXB6 and HOXB9, HOXB3 with HOXB4 and HOXB5 and HOXB6, HOXC8 with HOXC9, HOXC9 with HOXC10, HOXD10 with HOXD11." (PMID 39980564, 2025). "Analysis of DEHGs in oncogenic pathways using GSCALite26 indicated that HOXD10, HOXD11, HOXD1, HOXC4, HOXC10, and HOXA11 may have a crucial role in the activation of epithelial-mesenchymal transition (EMT) in cancer, represented in the form of heatmap percentage." (PMID 35562533, 2022).
HOXC10 also shares sentences with these, for which no sentence is quoted: cervical carcinoma (2 papers); cervical squamous cell carcinoma (2); acute myeloid leukaemia (1); atherosclerosis (1); gastrointestinal tumors (1); infection (1); leukemia (1); mouth neoplasms (1); multiple myelomas (1); osteosarcoma (1); pancreatic ductal adenocarcinoma (1); squamous cell carcinoma (1).